MAPT (microtubule associated protein tau)
Diseases named in the same sentence as MAPT in open-access papers (continued):
Sharing a sentence is not in itself a finding about the gene and the disease.
dementia (187 papers, 2006 to 2026). Loss of intellectual abilities interfering with an individual's social and occupational functions. "Conversely, increased TDP-43 binding at exons 3 and 6 in the dementia-associated gene MAPT led to retention of those exons in transdifferentiated neurons, which is the expected alternative splicing pattern of MAPT in adults." (PMID 40456907, 2025). "This case highlights the pivotal role of biomarkers and genetic testing in differentiating atypical dementia phenotypes while providing novel evidence for MAPT mutation-associated phenotypic diversity in Asian populations." (PMID 41399730, 2025). "The loci highlighted by LAVA further strengthen this theory, as GBA1 variants are commonly associated with worse cognitive outcomes in PD patients, and it has been suggested that MAPT is associated with dementia in PD25." (PMID 39639040, 2024). "The NET-PDD study longitudinally assesses newly-diagnosed PD patients in two subgroups at low and high dementia risk (stratified based on pentagon copying, semantic fluency, MAPT genotype), with comparison to age- and sex-matched controls." (PMID 37757857, 2024). "Temporal lobe volumes show the fastest decline over time even in presymptomatic MAPT mutation carriers, and it was even more accelerated in those who converted to dementia, who also showed frontal and parietal longitudinal atrophy." (PMID 38592608, 2024). "The H1 haplotype, known as MAPT H1, has been associated with poor cognitive performance and conversion to dementia in PD cohorts." (PMID 37214541, 2023). "This was confirmed in patients with early PD vs. controls (n = 41, each group) especially in those at risk of developing early dementia, determined by microtubule-associated protein tau (MAPT) genotype and neuropsychological predictors." (PMID 38269112, 2023). "As a proof-of-concept, we introduced a dementia-related splice-switching mutation in the Microtubule-Associated Protein Tau (MAPT) exon 10 splicing reporter." (PMID 37566038, 2023). "In the familial forms of the primary tauopathy FTLD-tau, the disease is caused by autosomal dominant mutations in the tau-encoding MAPT gene, demonstrating that tau dysfunction by itself can lead to neurodegeneration and dementia." (PMID 36316035, 2023). "Hyperphosphorylated microtubule-associated protein tau has been implicated in dementia, epilepsy, and other neurological disorders." (PMID 36459557, 2022). "No additional variants were detected in PSEN2, APP, or other dementia causative genes (e.g., MAPT, GRN, and TARDBP)." (PMID 35932032, 2022). "Mutations to the MAPT gene that encodes tau have been implicated in the development of dementia and increased phosphorylation at positions Ser-396, Ser-400, Thr-403, and Ser-404." (PMID 35031916, 2022). "Histologically, dementia is characterized by an abundance of Aβ plaques in the brain and an increased presence of the hyperphosphorylated form of microtubule-associated protein tau (pTau) aggregates within the neurons." (PMID 36145091, 2022). "We analyzed baseline visit data of known carriers of a pathogenic variant in the c9orf72, GRN, or MAPT gene from the Genetic Frontotemporal Dementia Initiative cohort study." (PMID 35948443, 2022). "Microtubule-associated protein tau lesions show higher associations with dementia severity than Aβ plaques; thus, targeting pathogenic tau protein is very effective in clinical treatment." (PMID 35946309, 2022). "A family history of dementia is found in 25–50% of the FTD patients with microtubule-associated protein tau (MAPT) and progranulin (GRN) mutations, and chromosome 9 open-reading-frame 72 (C9orf72) expansion as major pathogenetic determinants." (PMID 35672480, 2022). "PPI network that demonstrated proteins such as PSEN1, PSEN2, APP, MAPT, and C9orf72 had abundant interactions with other proteins, which was consistent with the important roles of these dementia pathogenic genes." (PMID 34720994, 2021).
dementia (continued). "In this study, we investigated the association of SNPs in the APOE and MAPT loci with time to dementia by retrospective survival analysis in neuropathologically defined PD brain donors." (PMID 33613437, 2021). "More than 50 pathogenic mutations have been identified in the MAPT gene, some of which have been linked directly to early onset familial forms of dementia (such as FTDP-17), establishing that tau alterations alone can cause neurodegeneration." (PMID 33986302, 2021). "One study analyzing an SNCA risk allele combined with the MAPT H1-haplotype suggests they cause a synergistic increase in the susceptibility of developing dementia in patients with PD." (PMID 34833115, 2021). "For instance, human genetic studies reveal that around 50 distinct mutations in MAPT, the gene that encodes tau, cause inherited forms of dementia with evidence of tau filaments." (PMID 33712082, 2021). "Common genetic variation of the apolipoprotein E (APOE) ε4 allele and microtubule-associated protein tau (MAPT) H1-haplotype have been linked to earlier development of dementia in patients with PD." (PMID 34833115, 2021). "The MAPT H1-haplotype was also significantly associated with a shorter time to dementia (HR per H1 haplotype 1.71, 95% CI 1.06–2.78, p = 0.03)." (PMID 33613437, 2021). "The underlying mechanisms linking APOE and MAPT variants to dementia are unclear, however neuropathological studies suggests that protein aggregation is pivotal in this association." (PMID 33613437, 2021). "In a 5-year follow-up study, the MAPT H1/H1 genotype was proven to be an independent predictor of dementia risk in PD patients." (PMID 33459970, 2021). "Cumulative evidence indicates that correct splicing (balanced 3R/4R ratio) is required for normal neuronal function: several MAPT mutations causing overproduction of 4R tau (inclusion of exon 10) have effectively triggered neurodegeneration linked to dementia." (PMID 34274950, 2021). "Some heterogeneities such as the microtubule-associated protein tau (MAPT) genotype and apolipoprotein E subtype influence development of dementia in PD." (PMID 33551789, 2020). "Our finding here of disruption of the neuronal nuclear membrane as a consequence of MAPT mutations in FTD extends this pathogenic mechanism to dementias in which protein aggregation has been thought to be the primary driver of neurodegeneration." (PMID 30650353, 2019). "The neuronal microtubule-associated protein tau, MAPT, is central to the pathogenesis of many dementias." (PMID 30650353, 2019). "P10636 (microtubule-associated protein tau, that is involved in diseases like dementia etc.)was found to be the commonly screened target by about seventy percent of these phytochemicals." (PMID 29320554, 2018). "Tau has been found to co-localize with α-synuclein and MAPT polymorphism is associated with increased risk of dementia in Parkinson’s disease." (PMID 30137209, 2018). "So far, our commitment to improving the GO resource for dementia-relevant research has focussed on amyloid-beta, the microtubule-associated protein tau and its interacting partners, as described here." (PMID 30501127, 2018). "We will then focus on two PD susceptibility genes, namely, glucocerebrosidase (GBA) and microtubule-associated protein tau (MAPT), both of which influence progression to dementia in PD." (PMID 27242557, 2016). "Inheritance of one allele of MAPT with the N279K mutation is causal to the development of pre-geriatric dementia, in the form of FTDP-17." (PMID 26373282, 2015). "One study did suggest a synergistic increase in the susceptibility of developing dementia in patients with PD when a SNCA risk allele was analyzed with MAPT H1/H2 inversion polymorphism." (PMID 25352339, 2014). "Mutations that cause abnormality in the splicing elements in the MAPT gene produce irregular ratios of MAPT transcripts observed in patients affected with an inherited form of dementia." (PMID 24179441, 2013).
dementia (continued). "Mutations in the APP, PSEN1, PSEN2, and MAPT genes give rise to well-characterized differential neuropathological and clinical phenotypes of dementia." (PMID 22482072, 2012). "The microtubule-associated protein tau (MAPT) is a pathological component of several neurodegenerative diseases and clinical dementias." (PMID 16930453, 2006). "However, an opposite effect was observed for cognitive outcomes in MAPT variant carriers, such that females with dementia exhibited less cognitive decline than males with dementia (P < 0.001)." (PMID 40277077, 2025). "However, dysregulation of splicing in genes like microtubule- associated protein tau (Mapt) can lead to neurodegeneration and dementia." (PMID 41009380, 2025). "In prodromal FTD and presymptomatic mutation carriers (GRN, MAPT, C9orf72), elevated NfL may herald pheno-conversion to full-blown dementia." (PMID 39519389, 2024). "Semantic dementia, albeit with behavioral features, is also a possible phenotype of MAPT mutations." (PMID 38592608, 2024). "In addition, whole genome sequencing has identified other genetic risk variants involved in APP and tau metabolism (such as ADAM10, ADAMTS1, and MAPT) or genes associated with dementia (e.g., CSF1R, GRN, and ARSA)." (PMID 39061930, 2024). "Moreover, it has been reported that microtubule-associated protein tau (MAPT) H1 haplotype carriers present a higher risk of dementia, are less accurate with difficult spatial rotations, and show lower activity in the parietal cortex and caudate nuclei." (PMID 37626529, 2023). "Two families were negative for DIAD variants or other genes associated with autosomal dominant cause of dementia (e.g., MAPT, GRN, TARDBP, FUS), probands on those families were APOE4 carriers; 11 families are undergoing additional genetic counseling for future genetic testing." (PMID 35932032, 2022). "Besides smaller variants in MAPT, a rare duplication encompassing the MAPT locus is known to underlie some cases of early-onset dementia resembling AD clinically." (PMID 35393555, 2022). "With the advantages of definite diagnosis and clinical data from the patients' entire lifespan, we found that even in a small sample, both the APOE ε4 allele and the MAPT H1-haplotype were significantly associated with an accelerated onset of dementia in PD patients." (PMID 33613437, 2021). "Alzheimer’s disease (AD) is the most common age-related form of dementia, associated with deposition of intracellular neuronal tangles consisting primarily of hyperphosphorylated microtubule-associated protein tau (p-tau) and extracellular plaques primarily comprising amyloid- β (Aβ) peptide." (PMID 31942037, 2021). "We also found a significant association between MAPT H1 and time to dementia in PD." (PMID 33613437, 2021). "Additionally, H1 haplotype-specific variation in the MAPT 3′ UTR is associated with tangle-only dementia." (PMID 33121065, 2020). "In this work, we combined gene expression data for 16 772 genes from the Allen Institute for Brain Science atlas with brain maps of grey matter atrophy in symptomatic C9orf72, GRN and MAPT mutation carriers obtained from the Genetic Frontotemporal dementia Initiative study." (PMID 33210084, 2020). "We cannot find any research that investigates roles of MAPT1 in learning and memory, but there is evidence that a MAPT mutation may be indirectly associated with cognitive dysfunction observed in dementia." (PMID 31699891, 2019). "Characteristics of the cohort of dementia patients analysed for mutations in MAPT, GRN and C9ORF72." (PMID 27632209, 2016). "MAPT mutations on exons 1, 9, and 11 to 13 account for the dementia-dominant phenotype." (PMID 21416021, 2009). "In addition, the rare MAPT A152T variant has been associated with the development of an AD-like dementia, suggesting that the locus may play a role in modifying AD risk." (PMID 36337698, 2022).
dementia (continued). "However, certain MAPT mutations can cause increased exon 10 inclusion, resulting in an overproduction of 4R isoforms and an imbalance of the 3R/4R ratio, which is enough to cause neurodegeneration and dementia." (PMID 28319892, 2017). "To begin to expand the utility of these iPSC lines for researchers in the dementia fields, we used CRISPR/Cas9‐mediated genome editing to introduce pathogenic MAPT mutations into the newly characterized iPSC lines." (PMID 40219788, 2025). "In MAPT carriers, females with dementia exhibited a more rapid functional decline (P < 0.001) and increase in plasma NfL (P = 0.001) than males with dementia across the study course." (PMID 40277077, 2025). "Within the context of gene and RNA-based therapies for AD and other dementias, at present therapies are specific to a single gene mutation (e.g., GRN) or proteinopathy (e.g., MAPT) to ensure clear evidence regarding safety and efficacy." (PMID 40634156, 2025). "Of the genes/proteins associated with dementia, six are consistent with the results obtained from VOSviewer: APP, MAPT, APOE, ACE, IL6, and CRP." (PMID 40699836, 2025). "In cases of prodromal FTD and presymptomatic mutation carriers (GRN, MAPT, C9orf72, TARDBP), elevated NfL concentrations appear to be a harbinger of pheno-conversion to full-blown dementia." (PMID 39519389, 2024). "Her early work focused on Mendelian forms of dementia and led to the identification of mutations in APP, PSEN1, and MAPT as causes of AD and FTD." (PMID 38170841, 2024). "The 3xTg-AD mouse model expresses three genes associated with dementia: PSEN1 m 146 V, APPSwe, and microtubule-associated protein tau (tauP 301 L)." (PMID 39273520, 2024). "Variants in ApoE, GBA, MAPT, α-synuclein (SNCA) have been proven to be associated with cognitive decline and dementia in PD." (PMID 38988604, 2024). "Chi-square, t-tests, and analyses of covariance examined associations between the presence of the MAPT H1 haplotype, cognitive diagnoses of normal, mild cognitive impairment (MCI), and dementia, and performance in specific cognitive domains." (PMID 37214541, 2023). "An interesting link to monogenic dementia has recently been revealed, as DCTN1 has been found in a yeast two-hybrid screen to directly interact with APP and tau (encoded by MAPT), suggesting that these three proteins are linked at a molecular level." (PMID 37330543, 2023). "Genetic risk factors of dementia by APOE ε4 and MAPT (rs242557) A allele were associated with variations of cortical morphology, which can be observed in young healthy adults more than 30 years before Alzheimer’s pathology is likely to occur and 50 years before dementia symptoms may begin." (PMID 37693814, 2023). "We reasoned that Tau protein expression and accumulation has a role in both dementias, and we set out to find which miRNAs directly regulate MAPT expression." (PMID 37324585, 2023). "Other differentially expressed genes have been previously associated with dementia (ITM2B, MAPT, ZNF267, and DHX37)." (PMID 34194426, 2021). "Here, we evaluate BMAA exposure by investigating transcription signatures using PCR for dolphin genes homologous to those implicated in AD and related dementias: APP, PSEN1, PSEN2, MAPT, GRN, TARDBP, and C9orf72." (PMID 34678990, 2021). "The results were confirmed in the subsequent 5- and 10-year follow-up studies, supporting the MAPT H1/H1 genotype as predictive of dementia." (PMID 33613437, 2021). "The microtubule-associated protein tau is the main component of neurofibrillary tangle (NFT) pathology in AD and other dementias." (PMID 32796905, 2020). "In our qualitative assessment of MAPT carriers, low tracer uptake was seen in two IVS 10 + 16 carriers diagnosed with MCI, while more prominent, widespread uptake was seen in MAPT carriers with dementia." (PMID 30704514, 2019).
dementia (continued). "Despite the clear association of MAPT mutations with FTLD-tau, we have little understanding of the downstream events that lead to neurodegeneration and dementia." (PMID 30546007, 2018). "Although tau mutations are not present in the most frequent cases of tauopathies, different mutations in MAPT have been found to cause FTDP-17 and PSP, demonstrating that alterations in tau function result in neurodegeneration and dementia." (PMID 29621183, 2018). "In summary, a complete screening for mutations in MAPT, GRN and C9ORF72 genes revealed a frequency of 5.4% of pathogenic mutations in a random cohort of 93 Turkish index patients with dementia." (PMID 27632209, 2016). "The reports of ALS in cases with MAPT and PGRN mutations have to be confirmed as does dementia in ALS resulting from SOD1 mutations." (PMID 24915640, 2014). "MAPT and PPP3R1 also showed weak associations with clinical AD, which suggest that they contribute to dementia risk." (PMID 23573206, 2013). "Although NFTs are also present in other dementias, they are still an important correlate of AD pathology and tau (MAPT) is a component of a toxic triad thought to mediate Aβ neurotoxicity." (PMID 23805206, 2013). "The identification of disease-causing mutations in the microtubule associated protein tau (MAPT) has established that tau dysfunction is sufficient to cause neurodegeneration and dementia." (PMID 23300938, 2012). "Pathogenic mutations in APP, PSEN1, PSEN2, MAPT and GRN have previously been linked to familial early onset forms of dementia." (PMID 22312439, 2012). "Using this tool, we performed thalamus segmentations in MRI scans from C9orf72, GRN and MAPT mutation carriers and mutation non-carriers with suitable 3-Tesla MRI cross-sectional data from the GENetic Frontotemporal dementia Initiative." (PMID 41245435, 2025). "APP, APOC1, APOE, SORL1, and MAPT are highly relevant common genes for AD and dementia." (PMID 38790243, 2024). "Notably, a few genes have come to light as important participants in the genetic architecture of dementia, including the presenilins (PSEN1 and PSEN2), the apolipoprotein E (APOE) gene, and microtubule-associated protein tau (MAPT)." (PMID 38607741, 2024). "Cluster 1 mainly presented alterations in MAPT and a higher percentage of people with APOE e4 allele (therefore, with a higher risk of developing dementia due to AD), as well as higher tau levels at the dementia stage." (PMID 38693203, 2024). "The potential link between MAPT gene duplication and early-onset uncommon dementia with tau accumulation should be further investigated and may correlate with neuroimaging findings." (PMID 40729198, 2023). "This hypometabolism pre-dates dementia in FTD linked Granulin (GRN) mutant carriers, spreads as disease progresses and in Microtubule-Associated Protein Tau (MAPT) -linked FTD patients closely maps to areas of toxic MAPT accumulation, suggesting it closely tracks disease development." (PMID 37733679, 2023). "Carriers of APOE ε4 and GBA mutations had faster cognitive decline and were at higher risk of progression to dementia, whereas no significant gene-related effects were observed for MAPT and SNCA rs356219." (PMID 38203667, 2023). "The main drawback is the need of using mutated MAPT gene (characteristic of other types of dementia) to model this disorder, even though AD patients do not show any tau-related mutation." (PMID 35628216, 2022). "Few studies have reported the impact of MAPT or rs356219 on the progression to dementia." (PMID 35106798, 2022). "Additionally, three studies reported associations in non‐AD dementias, namely, DLB and FTD patients with GRN, C9orf72 and MAPT mutations." (PMID 35338546, 2022). "We measured the complement proteins C1q and C3b in CSF by ELISAs in 224 presymptomatic and symptomatic GRN, C9orf72 or MAPT mutation carriers and non-carriers participating in the Genetic Frontotemporal Dementia Initiative (GENFI), a multicentre cohort study." (PMID 36064709, 2022).